IDH1 (isocitrate dehydrogenase (NADP(+)) 1)
Diseases named in the same sentence as IDH1 in open-access papers (continued):
Sharing a sentence is not in itself a finding about the gene and the disease.
glioma (continued). "Interestingly, a recent study demonstrated an additional vulnerability of IDH1/2 mutant gliomas with increased abundance of the oncometabolite D-2-HG, namely, sensitivity to histone deacetylases (HDACs) inhibitors." (PMID 35869047, 2022). "Although the use of LITT in the treatment of grades II and III glioma has increased over the last few decades for both primary and recurrent gliomas, to our knowledge, this is the first multi-patient study analyzing the outcomes of IDH1/2 mutant grade 2/3 gliomas treated with LITT." (PMID 35448183, 2022). "With this aim, we report herein the development of radioiodinated ((S)-[125I]2) and radiofluorinated ((S)-[18F]3) mIDH1 specific tracers for SPECT and PET imaging of low-grade gliomas and CHS, chosen as central as well as peripheral solid tumours most frequently harbouring IDH1 mutations." (PMID 35744895, 2022). "In addition, H3K27M mutation of other biomarkers and high expression of Ki67 and IDH1 wild-type glioma are related to the age of patients, thus affecting the survival probability." (PMID 36109699, 2022). "Considering these results might account for the IDH1 mutation occurring in glioma, we analyzed IDH1 in specific tumors, including LGG and GBM in the TCGA cohort; IDH1 exhibited the highest mutation frequency in TCGA LGG cohort (77%)." (PMID 36568190, 2022). "High AUC values in the ROC-analysis (0.783 for TBF and 0.791 for nTBF) indicate that ASL perfusion might be useful/informative in the differential diagnosis of gliomas with different IDH1 status." (PMID 35741254, 2022). "All the high-grade glioma investigated for IDH1 mutation were negative (n = 45) contrasting with the grade 1 glioma (n = 15) harboring IDH1 mutation in all cases based on Jiang 2020." (PMID 35267601, 2022). "Results from the current study provide the first evidence that early, transient changes in tumor vascularity may occur following IDH inhibition in human IDH1-mutant gliomas." (PMID 36033919, 2022). "It is reported that GDH accelerated proliferation of breast cancer and IDH1 mutant glioma." (PMID 36230806, 2022). "In preclinical models of IDH1-mut gliomas, long-term administration of DNA methyltransferase inhibitors (DNMTi), 5-azacitidine and decitabine, induced reduction of DNA methylation, glial differentiation, and a significant tumor growth inhibition in xenograft models." (PMID 35267433, 2022). "None of the 47 NF1-associated gliomas in this cohort had IDH1 or IDH2 mutation, EGFR amplification, TERT promoter mutation, or histone H3 p.G34 mutation." (PMID 35945463, 2022). "The serum lymphocyte count in LGG patients was significantly higher than in HGG patients, regardless of glioma type, IDH1 mutation, or wild-type status (P<0.05)." (PMID 36147928, 2022). "The decrease in metabolic activity we found after treatment with these agents complies with our data after esiRNA-mediated NAMPT inhibition, as well as reports of decreased levels of NAD+, NADH, NADP+ and NADPH in glioma cells with and without IDH1 mutation." (PMID 35628596, 2022). "The specific inhibition on DHODH, the key enzyme of pyrimidine synthesis, could have a very good effect on the treatment of patients with IDH1 mutant glioma." (PMID 36568190, 2022). "Moreover, the IDH1 mutant had been widely recognized as one of the indicators for molecular typing of glioma." (PMID 36111134, 2022).
glioma (continued). "Effect of MIL normalisation on accuracy of radiomics model for glioma grading, for isocitrate dehydrogenase 1 (IDH1) prediction (a key genetic marker of adult-type diffuse glioma that has prognostic and diagnostic qualities), and on tumour segmentation was assessed." (PMID 35486171, 2022). "Notably, a comprehensive metabolism investigation was performed on clinical IDH1 mutant glioma specimens." (PMID 35912242, 2022). "The introduction of mutant IDH1 or treatment with 2-HG in immortalized normal human astrocytes and syngeneic mouse glioma models led to a reduction of CXCL10 levels, which was associated with decreased production of STAT1 and also suppressed the accumulation of T-cells into tumors." (PMID 35267433, 2022). "However, this specificity should be further investigated by including IDH1‐wild‐type cell lines and a mouse model of IDH1‐wild‐type glioma in order to provide additional evidence for our findings." (PMID 34856072, 2022). "Recent studies revealed that IDH1 mutant gliomas showed CpG island methylator phenotype (CIMP)." (PMID 35260196, 2022). "Finally, exogenous R132H IDH1 expression in a resistant IDH wildtype cell line recapitulated the JQ1-mediated delayed cytotoxicity seen in our endogenous IDHmut glioma cells." (PMID 35467128, 2022). "Additionally, BIRC5 expression is also associated with histology subtypes, IDH1 mutation, 1p/19q chromosomal co-deletion, chemotherapy status, and MGMT promoter methylation status, well-established molecular characteristics of gliomas." (PMID 35309512, 2022). "In addition, this study identified novel methylation loci associated with glioma CIMP that have the potential to refine the utility of WGMA assessment to detect CIMP and predict IDH1/IDH2 mutation status." (PMID 36360312, 2022). "Furthermore, mutant IDH1 inhibitor led to increased survival in preclinical glioma models and led to increased CXCL10 expression and TILs." (PMID 35203421, 2022). "Immune infiltration is lower in Mutant IDH1/2 gliomas than in wild-type IDH1/2 gliomas." (PMID 35769466, 2022). "In contrast, a previous study of 14 cases of multicentric glioma finds no IDH1 mutation or ATRX loss." (PMID 35806978, 2022). "For instance, under hypoxic conditions, decreased reductive glutamine metabolism was only found in gliomas with IDH1 mutations but not IDH2 mutations." (PMID 36295820, 2022). "Gliomas with IDH1 and IDH2 mutations had a better prognosis than wild-type gliomas." (PMID 36561336, 2022). "IDH1 status assessment was performed after tumor removal in 106 cases—48 patients were diagnosed with wildtype gliomas (Grade 1–2—6 patients, Grade 3–4—42 patients) and 58 patients were diagnosed with mutant forms of gliomas (Grade 1–2—28 patients, Grade 3–4—30 patients)." (PMID 35741254, 2022). "Our analysis shows frequent mutations of IDH1 and IDH2 in the TCGA LGG (lower grade glioma) cohort and frequent amplifications of IDH1 in LIHC (liver hepatocellular carcinoma), as well as less frequent mutations and amplifications of IDH1 in CHOL, GBM, PRAD and SKCM." (PMID 35975235, 2022). "There were many radiomics studies involving HER2 in breast cancers and IDH1 in gliomas." (PMID 36267986, 2022). "For instance, analysis of 2-HG by proton MRS is shown to correlate with either IDH1 or IDH2 mutations in the tumor, suggesting that elevated 2-HG levels in IDH-mutated gliomas may one day offer crucial diagnostic and prognostic data." (PMID 36654821, 2022). "In addition, DNMT1i azacytidine represses the growth of IDH1 mutant gliomas in vivo, accompanied by hypomethylation and marked cellular differentiation, with no tumor recurrence observed up to 7 weeks after drug withdrawal." (PMID 35203421, 2022).
glioma (continued). "U87 human high-grade glioma (HGG) isogenic cell lines with or without the IDH1 mutation (CRISP/Cas9 method) were stereotactically grafted into rat brains, and examined, in vitro, in vivo and ex vivo." (PMID 35303961, 2022). "As might be expected, heterozygous mutations in the catalytic arginine residues of isocitrate dehydrogenase gene (IDH1/2) are common in gliomas and acute myeloid leukemia, and contribute to the pathogenesis of several tumors." (PMID 36426134, 2022). "Furthermore, we also identified differently expressed genes between IDH1-mutant and IDH1 wildtype gliomas, which is a crucial regulator in glioma progression." (PMID 35341001, 2022). "Therefore, accurate identification of glioma IDH1 genotype facilitates the formulation of treatment plans and assessment of patient prognosis." (PMID 34880724, 2021). "Greater rates of non-canonical IDH1 mutations have been reported in infratentorial gliomas compared to supratentorial gliomas, and in lower grade gliomas overall." (PMID 34587990, 2021). "Interestingly, Unruh and colleagues found higher levels of EVTF activity in glioma patients with wild-type IDH1/2 compared to glioma patients with mutant IDH1/2." (PMID 34359742, 2021). "To verify that previous identified prognostic genes of TCGA-glioma PTEN-mut are also the prognostic genes in IDH1-wt patients with PTEN-mut, we observed that AEBP1, CLCF1, and OS9 were significantly prognostic genes in IDH1-wt, IDH1-wt/GBM, or IDH-wt/LGG gliomas with PTEN-mut." (PMID 34336645, 2021). "D2HG quantitation via ELISA also showed that 0905 and TB096 cell lines produced higher levels of D2HG, whereas BT142 more closely resembled IDH1/2wt glioma cells, consistent with prior studies indicating that both IDH1wt and IDH1mut alleles are required for prominent D2HG production." (PMID 34424450, 2021). "In addition, seizure was more likely to occur in the gliomas patients with IDH1mut than IDH1 wild-type (IDH1wt) patients." (PMID 33795525, 2021). "Glioma patients with wild-type IDH1/2 have a higher rate of VTE than patients with mutant IDH1/2." (PMID 34359742, 2021). "In addition, despite using slightly different statistical cutoffs and models, several age-associated genomic features are identified by both studies, for example, the higher frequency of IDH1 and ATRX mutations in younger glioma patients." (PMID 33879792, 2021). "IDH-mutant gliomas exhibit a cytosine-phosphate-guanine (CpG) island methylator phenotype (G-CIMP) characterized by a genome-wide hypermethylation induced directly by mutant IDH1." (PMID 34067729, 2021). "In gliomas with IDH1R132H mutations, drugs that inhibit the mutant IDH1 enzymes may improve 2-OGDD activity by reducing 2-HG production." (PMID 33842321, 2021). "Due to tumour heterogeneity among glioma patients, TMEFF2 methylation may be a biomarker of poor prognosis in IDH1 mutant glioma patients." (PMID 33663520, 2021). "With one exception, all IDH1-mutated gliomas were methylated, while none were methylated in the other group." (PMID 34885053, 2021). "In total, 30/34 (88%) gliomas had no mutation of the IDH1/2 gene and were classified as WHO grade 4." (PMID 35008218, 2021). "Other small IDH inhibitors such as olutasidenib (FT-2102) are currently under investigation in phase I/II clinical trials for AML and myelodysplastic syndrome as well as vorasidenib (AG-881), a pan inhibitor of both IDH1/2 enzymes, has been evaluated in glioma (NCT04164901)." (PMID 34070384, 2021). "Generally speaking, glioma patients with the IDH1 mutation have a more favorable prognosis, and the mutation is frequently expressed in patients with an LGG but rarely detected in patients with a WHO grade 4 glioma." (PMID 34733261, 2021). "However, in combination with IDH1 and MGMT mutations, these mutations are good predictors of grade II and grade III gliomas." (PMID 33916593, 2021).
glioma (continued). "Our study showed the IDH1 mutation rate in the STR group was 13.3%, which was extremely lower than in the LTR group (73.7%), and IDH1 wild type was confirmed as an independent risk factor for short-term glioma recurrence." (PMID 34778058, 2021). "In IDH1 wild-type gliomas, chr10 deletion coexisted with chr7." (PMID 34093830, 2021). "Patients with IDH1-mutant glioma were younger than those with IDH1 wild-type glioma (P = 0.008)." (PMID 34880724, 2021). "Our observation that non-R132H IDH1/2-mutated 1p/19q non-codeleted gliomas have a more favourable prognosis than their IDH1R132H mutated counterpart is clinically relevant and should be taken into account for patient prognostication." (PMID 33740099, 2021). "Although IDH1 and IDH2 mutations are associated with better OS in glioma patients, it is controversial whether OS has a good correlation with chondrosarcoma patients." (PMID 33981605, 2021). "In addition, several clinicopathological and molecular features determine the outcome of patients with gliomas, such as WHO grade, isocitrate dehydrogenase 1/2 (IDH1/2) mutations, 1p/19q co-deletion, MGMT promoter methylation, subtype." (PMID 35223862, 2021). "Therefore, it is important to monitor 2HG as the direct metabolite of IDH1 mutant glioma along with metabolomics monitoring of immune cells in glioma patients." (PMID 34150663, 2021). "Also in the MSK-Impact and the Chinese Glioma Genome Atlas (CGGA) there were too few samples and events to determine survival benefit in patients harbouring non-R132H IDH1/2–mutated tumours." (PMID 33740099, 2021). "To confirm these observations, we performed a similar analysis on the IDH1/2 mutated, 1p/19q non-codeleted glioma patients included in the TCGA dataset." (PMID 33740099, 2021). "Furthermore, recent reports have documented that MET uptake in IDH1-wildtype gliomas is significantly higher compared with that in IDH1-mutant gliomas." (PMID 34743250, 2021). "Additionally, the expression of GCH1 and FSP1 increased with increasing malignancy of the tumor; GPX4, FSP1, and GCH1 were highly expressed in patients with glioma and wild-type IDH1 compared to mutant IDH1." (PMID 35174170, 2021). "Finally, JHU-083 extended survival in an intracranial IDH1 mut glioma model and reduced intracranial pS6 protein expression." (PMID 33681764, 2021). "However, very few studies have investigated the interplay between IDH1 mutations and WNT signaling in gliomas and thus, the repercussion in gliomas development." (PMID 34070746, 2021). "IDH1 mutations had developed through progression from an anaplastic glioma (WHO Grade III), while the majority of secondary GBM with IDH1 mutations had progressed from a WHO Grade II glioma." (PMID 34070746, 2021). "recently demonstrated that the IDH1 R132H mutant pathway could also be targeted by a peptide vaccine approach in newly diagnosed gliomas." (PMID 34222022, 2021). "We therefore speculate that the lower glymphatic function of IDH1 wild-type gliomas may be related to their short duration of tumor growth, which does not allow extensive remodeling of the glymphatic pathway." (PMID 34631582, 2021). "We also investigated the prediction of glioma grading by dMRI under the same IDH1 genotype." (PMID 34880724, 2021). "In addition, a nomogram that combined the risk signature and clinicopathological factors (age, Karnofsky performance score, grade and IDH1 status) was established to predict 1-, 3- and 5-year survival rate of glioma patients." (PMID 34055619, 2021). "Static and dynamic FDG-PET was used to describe IDH1 genotype in gliomas." (PMID 33472598, 2021).
glioma (continued). "Additional mitochondria would also increase the lipid membrane content in cells, which could help explain the differences seen in the phospholipid composition of mutIDH1 and WT IDH1 gliomas." (PMID 35028610, 2021). "Moreover, to provide insights about the origin of gliomas, the mutational status of IDH1 serves as a prognostic factor in patients with WHO grade II and III gliomas and GBM." (PMID 34070746, 2021). "While IDH1 and TERTp mutations, and 1p/19q codeletion assigned as the truncal events during tumour evolution, RAS mutations in glioma may be an additional alterations to development." (PMID 34525976, 2021). "Therefore, we mined the human cancer data derived from 37 different types of cancers, finding a high rate of IDH1 and IDH2 mutations in a tissue-specific manner mainly in gliomas suggesting a role for these genes in carcinogenesis." (PMID 35996504, 2021). "The IDH1 and IDH2 gene mutations can be used in clinical practice as strong prognostic biomarkers in gliomas as they could predict better survival." (PMID 35996504, 2021). "Significantly higher amounts of gliomas without verifiable IDH1-R132H mutation showed vascular PSMA expression." (PMID 34209106, 2021). "We speculate that the microenvironment of IDH1 wild-type glioma is more complicated, such as cell swelling and vascular proliferation, so it exhibits greater heterogeneity of intra-voxel diffusion." (PMID 34880724, 2021). "MutIDH1R132H gliomas are reported to have reduced glucose uptake compared with WT IDH1 gliomas." (PMID 35028610, 2021). "Moreover, combined inhibition of KDM6A/B and HDACs was markedly more effective than individual treatments of IDH1-mutant gliomas." (PMID 34356864, 2021). "IDH1-R132H mutation leads to decreased activity of WNT/β-catenin pathway, that in turn curbs the elevated proliferation and migration observed in invasive gliomas." (PMID 34070746, 2021). "Many studies have indicated a better prognosis of IDH1-mutant gliomas than IDH1 wild-type gliomas." (PMID 34880724, 2021). "More recently, based on the sequencing results of large samples, it was found that about 60% to 80% of patients with grade II and III gliomas and most patients with secondary glioblastoma (GBM) had somatic mutations encoding isocitrate dehydrogenase genes, mainly IDH1 R132 mutation." (PMID 33981605, 2021). "Five of nine gliomas with preserved H3K27me3 were oligodendrogliomas that harbor non-canonical IDH1-R132L or IDH2-R172 mutations." (PMID 34020723, 2021). "In addition, molecular features, including isocitrate dehydrogenase (NADP(+)) 1/2 (IDH1/2) mutations, have been incorporated into the classification of gliomas." (PMID 34360836, 2021). "Some studies indicated that IDH1 mutation status could improve OS and PFS in grade II and III glioma." (PMID 34540662, 2021). "Moreover, in IDH1 wildtype and mutant gliomas, low ARL score indicated a better prognosis than those with high ARL score (p < 0.05)." (PMID 34211979, 2021). "Moreover, BCAT1 is also involved in the glycolytic metabolism and immune suppression of IDH1 wild-type gliomas, suggesting multiple roles that BCAT1 exerts in the malignant transformation of glioblastoma." (PMID 33493139, 2021). "Glutamate dehydrogenase 1 (GLUD1) and GLUD2, which catalyze oxidative deamination of glutamate to 2-OG, are significantly elevated in mutIDH1R132H glioma compared with WT IDH1 glioma, indicating the potential for increased glutamate utilization by the TCA cycle." (PMID 35028610, 2021). "The opposed interplay between IDH1 mutations and the canonical WNT/β-catenin pathway in gliomas could participate in better understanding of the observed evolution of different tumors and could reinforce the glioma classification." (PMID 34070746, 2021).